TLR4 (toll like receptor 4)
Diseases named in the same sentence as TLR4 in open-access papers (continued):
Sharing a sentence is not in itself a finding about the gene and the disease.
glioma (continued). "The release of specific cytokines that protect cells from apoptosis or lead to the ability of tumor cells to altogether evade immune detection may also be due to the expression of TLR4 on glioma cells." (PMID 25411122, 2014). "Furthermore, glioma cells and GSCs are responsive to LPS stimulation via TLR4." (PMID 28641579, 2017). "However, little is known about the function of LPS-induced TLR4 signaling in glioma CD133+ CSCs." (PMID 28881826, 2017). "Therefore, we investigated the function of TLR4 in glioma CD133+ CSCs." (PMID 28881826, 2017). "However, results from previous studies on TLR4 in glioma remain controversial." (PMID 28641579, 2017). "TLR4 might provide novel therapeutic approaches for patients with glioma." (PMID 28881826, 2017). "Nevertheless, the investigation of LCA, the TLR4/NF-κB signaling pathway, and TMZ resistance in gliomas is currently in the preliminary phase." (PMID 39708583, 2025). "Recently, curcumin has been shown to exert an anti-glioma effect in vitro, by inhibiting the inflammatory HSP60/TLR-4 signaling pathway." (PMID 41002413, 2025). "Glioma cells treated with curcumin reduced the expression of HSP60 and likely its release and interaction with TLR-4, hindering the activation of the downstream pro-inflammatory pathway, mediated by MYD88 and NF-κB." (PMID 41002413, 2025). "Based on Toll Like Receptor 4 (TLR4)/Nuclear Factor-κB (NF-κB) Exploring the effects of Licochalcone A (LCA) on the proliferation, invasion, and drug resistance of glioma cells through signaling pathways." (PMID 39708583, 2025). "Our study highlights that TREM1 modulates the TLR4/PI3K/AKT/mTOR signaling axis to regulate biological functions and the PMT process in glioma cells." (PMID 41394801, 2025). "Particularly, the NS ALLO has been shown to inhibit inflammatory signals induced by TLR-4, indicating the potential for ALLO to reduce the effects of glioma on the peritumoral environment, if targeted." (PMID 39202716, 2024). "We also observed an enrichment of the ANGPTL signaling pathway between glioma (mainly from Clusters C1) and TAM (Cluster C0), mediated by angiopoietin-like 2 (ANGPTL2) and toll-like receptor 4 (TLR4)." (PMID 38515213, 2024). "In particular, the TLR families, including TLR1, TLR2, TLR3, TLR4, TLR6, and TLR9, are highly expressed in the TME of glioma, both in vitro and in vivo, leading to neuroinflammation." (PMID 37723542, 2023). "TLR4 is also expressed in glioma CD133+ CSCs and TLR4 interaction with lipopolysaccharide (LPS) confers adriamycin (ADR) resistance in glioma." (PMID 36359776, 2022). "In glioma, elevated TLR1, TLR2, TLR4, TLR5, TLR6, and TLR9 expressions were observed in tumor cell lines and tissues compared with non-neoplastic brain tissues, particularly in the mesenchymal subtype of GBM." (PMID 34715891, 2021). "Activation of TLR3, TLR4, and TLR9 has been reported to reinforce the antitumor response to anti-PD-1/PD-L1 and exhibit immune checkpoint delayed resistance in glioma cells or animal models." (PMID 34715891, 2021). "Up to date, TLR2, TLR3, TLR4, TLR7, and TLR9 have been intensely studied in glioma, while less or missing information is available regarding the mechanisms of TLR1/TLR6 (dimerizes with TLR2), TLR5, TLR8 (dimerizes with TLR7), and particularly TLR10." (PMID 34715891, 2021). "TLR4 mRNA and protein expression have been detected in U118, U87, A172, and LN229 glioma cell lines." (PMID 34715891, 2021). "TLRs play an important role for the interaction of microglia with glioma cells promoting a pro-tumorigenic phenotype including TLR2, TLR4, and TLR7 signaling." (PMID 32912327, 2020). "Previously, GL261 cells have also been shown to express TLR2, TLR3 and TLR4, and TLR ligands have been used as treatments against established glioma." (PMID 30974896, 2019). "However, the expression and function of TLR4 in glioma CD133+ CSCs are unknown." (PMID 28881826, 2017).
glioma (continued). "GSCs upregulate interleukin 6 (IL6) release from microglia via toll-like receptor 4 (TLR4) signaling, which enhances invasion and glioma growth." (PMID 28670569, 2017). "In our present study, activation of the TLR4 signaling pathway promoted the production of IL-1β, IL-6, IL-10, MCP-1, MIP-1α, and TNF-α in glioma CD133+ CSCs." (PMID 28881826, 2017). "Thus, TLR4 expression in glioma CD133+ CSCs may lead to cancer progression and immune evasion." (PMID 28881826, 2017). "TLR2, TLR4, and TLR9 have been under investigation for expression on glioma cells, and their contribution to tumor development has been mostly described as tumor promoting." (PMID 25411122, 2014). "TLR4 RNA and/or protein expression has been detected in U118, U87, A172, and LN229 glioma cell lines." (PMID 25411122, 2014). "This cytokine actually induces TLR4 expression, via hypoxia inducible factor 1-α (HIF-1α), which results in the elevation of HMGB1 in glioma cells." (PMID 25411122, 2014). "In the case of TLR4 and TLR9 agonists, the recommendation is to remain cautious when considering their roles in anti-glioma therapies." (PMID 25411122, 2014). "Two TLR4 agonists, LPS and Spirulina complex polysaccharide, have demonstrated efficacy in mice with subcutaneous implantation of DBT and RSV-M gliomas, respectively." (PMID 25411122, 2014). "In glioma, LPS not only upregulates inflammatory mediators such as IL-8, CXCL8, and IL-1β to support tumorigenesis but also alters the immunophenotype of glioma cells and induces antitumor immunity via TLR4." (PMID 40444051, 2025). "Moreover, TLR2, TLR3, TLR4, TLR7, TLR8, and TLR9 have emerged as critical modulators of glioma biology." (PMID 41157253, 2025). "Molecular docking studies revealed the specific bioactive mechanisms of each fraction: CMP1 exerted immunomodulatory effects by interacting with TLR4 and DC-SIGN receptors and exhibited therapeutic potential for brain edema or glioma via targeted binding to AQP4." (PMID 41155515, 2025). "In vitro experiments substantiated the role of TREM1 in the proliferative and invasive processes of gliomas, demonstrating that TREM1 exerts its biological functions through the TLR4/PI3K/AKT/mTOR signaling axis, thereby facilitating the PMT transformation of glioma cells." (PMID 41394801, 2025). "However, TNFα◽-induced NF-κB activation in glioma cell lines (A172 and LN229) involves both MyD88 and TRIF and is partially dependent on TLR4." (PMID 40727443, 2025). "While the implication and interaction in glioma biology remains unelucidated, the dual inhibitory effect of ALLO and THDOC through GABA-AR on TLR-4 proinflammation pathways remains an exciting venture for future research into molecular targets of glioma and GBM hallmarks." (PMID 39202716, 2024). "It has also revealed that TLR-4 activation (1 μg/ml) stimulates the secretion of the inflammatory cytokines (TNFα and ILs) and up-regulation of specific stem cell markers, including CD34 and CD133 in human glioma U251 cells." (PMID 38698968, 2024). "p65 nuclear translocation by non-canonical TLR4 signal/activation of DNA repair genes is positively correlated with the survival of U87MG glioma cells, suggesting that p65 is a potential therapeutic target for the inflammasome." (PMID 37723542, 2023). "LPS-induced activation of TLR-4 signaling, which was detected in mouse brains, was also shown in C6 glioma cells, and those inflammatory responses were abolished by IOE treatment in C6 glioma cells." (PMID 36670940, 2022). "Toll-like receptor 4 (TLR4) signaling in microglia has been shown to induce the release of IL-6, a ligand of the signal transducer and activator of the transcription 3 (STAT3) pathway in gliomas, which is also involved in invasiveness." (PMID 33802571, 2021).
glioma (continued). "The experiments using the GL261 glioma mouse model were prompted by our previous results on the promotion of tumor growth involving TLR2, TLR4, and TLR7 signaling, and were driven by the assumption that TLR5 might detect host-derived molecules." (PMID 32912327, 2020). "In the glioma context, TLR4 and in particular TLR2 are mediators of glioma-GAM interactions." (PMID 32331440, 2020). "However, in glioma cell lines (A172 and LN229), TNFα-induced NF-κB activation is partially dependent on TLR4 and involves both MyD88 and TRIF." (PMID 31240216, 2019). "LPS-activated TLR4 signaling promotes the proliferation and chemoresistance of glioma CD133+ CSCs and triggers the release of various cytokines, resulting in the resistance of glioma CD133+ CSCs to CTL-induced lysis." (PMID 28881826, 2017). "However, as a coreceptor of TLR4, the expression of MD2 in gliomas and the roles played in tumor immunity remain largely unknown." (PMID 35372062, 2022). "In addition, since the overproduction of ROS triggered by LPS was ameliorated by IOE treatment in C6 glioma cells, our data suggest that IOE may target the TLR-4/MyD88/ROS/MAPKs or TLR-4/MyD88/ROS/NFκB pathways to prevent LPS-induced neuroinflammation." (PMID 36670940, 2022). "However, unlike LPS pretreatment, the antitumor effect of intratumoral LPS treatment was independent of TLR4 expression in the implanted glioma cells." (PMID 28641579, 2017). "In this study, by Western Blot analysis, we confirmed that TLR-4 was significantly increased in GBM patients tissue respect to control brain tissue, suggesting that the use of a TLR-4 antagonist could be able to induce anti-proliferative and antimigratory response in glioma tumors." (PMID 30680070, 2018). "Within the family of TLRs, TLR-2, TLR-4, and TLR-9 stand out with unique expression patterns in glioma cell lines, while TLR-7 and 8 remain absent in gliomas." (PMID 39202716, 2024). "Based on these results, C6 glioma cells pretreated with nontoxic concentrations of IOE (0.1 and 0.2 mg/mL) were evaluated for the LPS-induced expression of TLR-4 and MyD88." (PMID 36670940, 2022). "The capacity of glioma CD133+ CSC-reactive cytotoxic T lymphocyte to selectively kill CD133+ CSCs was reduced by LPS, and this effect was not apparent after TLR4 knockdown in CD133+ CSCs." (PMID 28881826, 2017). "Although engagement of TLR3 and TLR4 pathways alone, for example, may not be sufficient to eradicate tumors, targeting these receptors could be considered as a supplement to therapy until mechanisms of glioma cell suppression on microglia are more clearly understood." (PMID 25411122, 2014). "The upregulation of TLR4 and HMGB1 is synergistic and results in the increase of HLA-G, a non-classical HLA class I antigen that participates in glioma immune evasion." (PMID 25411122, 2014). "IL- 1β secreted from glioma cells was found to be responsible for the activation of TLR-4 and upregulation of high mobility group box 1 (HMGB1) protein, which eventually results in the increase of HLA-G, a non-classical HLA class I antigen that contributes to glioma immune evasion response." (PMID 34439380, 2021).
gram-negative bacterial infections (58 papers, 2006 to 2026). Infections caused by bacteria that show up as pink (negative) when treated by the gram-staining method. "Mutations in TLR4 are correlated with susceptibility to Gram-negative bacterial infections, and TLR4 deficiency has been shown to alleviate LPS-induced acute liver injury by suppressing the TLR4/MyD88/NF-κB signaling pathway." (PMID 41488647, 2025). "Two serotypes of bacterial LPS were analyzed, both TLR4 activators, and mimic responses to Gram negative bacterial infection, such as E. coli, which can cause gastro-intestinal diseases." (PMID 34446770, 2021). "Since earlier studies mainly have associated TLR4 sequence variants to the increased risk of Gram-negative bacterial infections, these findings were rather surprising." (PMID 33339376, 2020). "Genetic variants in the TLR4 have also been linked to gram-negative bacterial infection in neonates." (PMID 25722880, 2015). "TLR2-deficient macrophages have been shown to be hyporesponsive to Staphylococcus aureus peptidoglycan, and C3H/Hej mice with missense mutations of the TLR4 gene were highly susceptible to Gram-negative bacterial infection." (PMID 25967535, 2015). "Toll-like receptor-4 (TLR-4) has an important pattern recognition receptor that recognizes endotoxins associated with gram negative bacterial infections." (PMID 27398236, 2012). "The toll-like receptor-4 (TLR-4) is an important pattern recognition receptor that recognizes endotoxins associated with gram negative bacterial infections." (PMID 27398236, 2012). "TLR4-deficient mice have been shown to be susceptible to gram-negative bacterial infection." (PMID 25722880, 2015). "TLR4 plays a vital role in host defense against Gram-negative bacterial infections by recognizing lipopolysaccharides (LPS) and inducing inflammatory mediators to clear infection." (PMID 41869302, 2026). "This work provides evidence that L. rhamnosus CRL1505 and L. plantarum CRL1506 modulate macrophages’ TLR4-mediated immunotranscriptomic response, helping to improve protection against Gram-negative bacterial infections." (PMID 40141330, 2025). "The Gram-negative bacterial infection of the GIT activating the TLR4 signalling pathway in male rats also induces GLP-1 secretion from L cells expressing TLR4." (PMID 40592472, 2025). "Together, these findings suggest that LPS-activated TLR4 signaling is crucial for orchestrating the DLPs construction in response to Gram-negative bacterial infection." (PMID 40721684, 2025). "For example, in the case of a gram-negative bacterial infection, toll-like receptors 4 (TLR4) is activated by lipopolysaccharide (LPS) molecules on the bacteria’s surface." (PMID 37986183, 2023). "Injection of LPS into rodents mimics the imperative aspects of Gram-negative bacterial infections, such as activating the Toll-like receptor 4 (TLR-4, pattern recognition receptor)." (PMID 36557252, 2022). "During Gram-negative bacterial infection, LPS stimulates the production of G-CSF, which is a glycoprotein, leading to the acceleration of granulopoiesis, and this phenomenon depends on TLR4-expressing endothelial cells." (PMID 33763386, 2021). "During Gram-negative bacterial infection, LPS stimulates the production of G-CSF, leading to the acceleration of granulopoiesis, and this phenomenon depends on TLR4-expressing endothelial cells." (PMID 33763386, 2021). "It has also been reported that in NSCLC patients with gram-negative bacterial infections, the excessive activation of the TLR4/IL-33 axis promotes tumor progression." (PMID 34457117, 2021). "We show Gram-negative bacterial infection upregulates Siglec-E expression via the TLR4/MyD88/JNK/NF-κB/AP-1 signaling pathway, whereas infection with Gram-positive bacteria downregulates Siglec-E expression via the TLR2/RANKL/TRAF6/Syk signaling pathway." (PMID 32889432, 2020).
gram-negative bacterial infections (continued). "Acute systemic Gram-negative bacterial infections are accompanied by release of lipopolysaccharide (LPS) endotoxins into the bloodstream and an innate immune host response via the well-known toll like receptor 4 (TLR4) pathway." (PMID 32038655, 2020). "As a member of PRRs, Toll-like receptor 4 (TLR4) plays an important role in Gram-negative bacterial infection elimination and inflammatory response initiation." (PMID 32760682, 2020). "In Gram-negative bacterial infection and due to LPS molecules, TLR4 was reported to play a role in recognition of enteric pathogens." (PMID 33212859, 2020). "Gram-negative bacterial infection leads to the release of LPS, which are recognised by toll-like receptor 4 (TLR4) on macrophages, subsequently triggering the overexpression of cytokines and an uncontrolled inflammatory response, leading to sepsis." (PMID 30846839, 2019). "In NSCLC patients, higher TLR4 expression was associated with increased IL-33 expression, Ki-67 proliferation index and CD133 expression in those with gram-negative bacterial infection." (PMID 29568370, 2018). "Herein, we extended previous studies by demonstrating that gram-negative bacterial infection led to high expression of IL-33 in NSCLC cells through TLR4 activation." (PMID 29568370, 2018). "Signal transduction following recognition of LPS by the TLR4 complex (CD14–TLR4–MD2) is an essential component of host immunity to Gram-negative bacterial infection." (PMID 28348558, 2017). "Toll-like receptor 4 (TLR4) plays a key physiologic role in host response to Gram-negative bacterial infection." (PMID 27618029, 2016). "Even though TLR4 is an essential factor in the innate immune response to Gram-negative bacterial infections, expression of this PRR in response to A. pleuropneumoniae infection has not previously been extensively characterized." (PMID 26018580, 2015). "Highly purified LPS, as was used in these experiments, is a selective TLR-4 agonist, a receptor that is essential for the host defense against Gram-negative bacterial infections." (PMID 26218271, 2015). "TLR2 and TLR4 are components of the innate immune response and play a crucial role in host defense against Gram-positive and Gram-negative bacterial infection." (PMID 26147469, 2015). "LPS or endotoxin, derived from gram-negative bacteria almost exclusively activates its primary receptor TLR4, one of the most studied pathways in host innate immunity against gram-negative bacterial infection." (PMID 25722880, 2015). "Interestingly, TLR4 deficiency led to a reduction in the inflammatory response without affecting bacterial colonization in placenta, suggesting a possible use of TLR4 agonists as co-adjuvant of antibiotic therapy in the treatment of women with Gram negative bacterial infections during pregnancy." (PMID 25688342, 2014). "TLR4 is an important Toll-like receptor (TLR) which responds to common Gram-negative bacterial infections." (PMID 23056598, 2012). "Innate immunity mediated by TLR4 also triggers the first-line host defense response to Gram-negative bacterial infections and is crucial for initiating subsequent T cell-mediated adaptive immune responses." (PMID 23170858, 2012). "A remarkable feature of TLR2 and TLR4 is their ability to cooperate with CD14 on the host cell surface in sensing LPS of Gram negative bacterial infection." (PMID 23492674, 2011). "For example, the response of a macrophage responding to a danger signal during a gram-negative bacterial infection involves innate pathogen recognition of LPS by the TLR4 complex." (PMID 17940599, 2007). "TLR4 is a known sensor of Gram-negative bacterial infections through recognition of the LPS." (PMID 40821781, 2025). "TLR4-dependent platelet–neutrophil interaction is responsible for the removal of intravascular bacteria by forming neutrophil extracellular traps (NETs) during Gram-negative bacterial infections." (PMID 36936237, 2023).